NFATC2 (nuclear factor of activated T cells 2)
Diseases named in the same sentence as NFATC2 in open-access papers (continued):
Sharing a sentence is not in itself a finding about the gene and the disease.
melanoma (continued). "Finally, to investigate the role of pathways that may be involved in NFATc2 regulation we focused on the ERK pathway, since MEK inhibition has been shown to downregulate NFATc2 gene expression in melanoma cells." (PMID 30710146, 2019). "Since we found that CTHRC1 is coordinately expressed with the transcription factor NFATC2 in melanoma cell lines, and the NFATC2 protein has been found to be expressed by melanoma cells in vitro and in vivo, we studied whether NFATC2 induces the expression of CTHRC1." (PMID 26918341, 2016). "Intriguingly, DAPL1 controls NFATc2 activation to regulate CD8 + T cell exhaustion and responses in chronic infection and cancer, including melanoma." (PMID 38980592, 2025). "Many of the identified fitness genes such as NFATC2 and EGLN1 have an as yet undetermined role in melanoma biology." (PMID 32767816, 2021). "IL-8 is a downstream target of nuclear factor of activated T cell (NFAT1, NFATC2), a transcription factor with important roles in adaptive and innate immune responses as well as in melanoma progression and metastasis." (PMID 35011682, 2021). "Expression of NFATc2 and of EMT-related markers was then investigated by immunohistochemistry (IHC) in human melanoma lesions." (PMID 30710146, 2019). "Pharmacological co-targeting of NFATc2 and EZH2 exerted significant anti-tumor effects in distinct melanoma subsets, including BRAF-mutant but BRAF-inhibitor-resistant cell lines, as well as NRAS mutant and BRAF/NRAS wild-type tumors." (PMID 30710146, 2019). "NFATc2 showed a positive correlation with AXL, SNAI1, CDH2, and ZEB1 even in the TCGA melanoma dataset." (PMID 30710146, 2019). "However, NFATC2 and TFAP2C, key markers of the AP2 invasive state identified in the Tirosh data, were broadly expressed throughout the Rambow melanoma cells." (PMID 38183207, 2025). "Additionally, these cells exhibited amplification of the transcription factor NFATC2, which is a recently-discovered gene controlling the EMT-like/invasive melanoma program by regulating downstream targets such as c-Myc, FOM1, and EZH2." (PMID 34837846, 2022). "Importantly, combined inhibition of NFATc2 and EZH2 (i.e., AM404+GSK126, respectively) reversed melanoma phenotype switching overnight." (PMID 34604096, 2021). "Similarly, pharmacological inhibition of NFATc2, a transcription factor that acts upstream of BRN2, drove a melanoma cell switch to a more differentiated state with decreased invasiveness." (PMID 34604096, 2021). "Crucially, pharmacological co-targeting of NFATc2 and EZH2 exerted significant anti-tumor activity not only against BRAF-mutant melanomas with intrinsic resistance to BRAF inhibitors, but even against NRAS-mutant and BRAF/NRAS wild type melanoma cells." (PMID 30710146, 2019). "In the TCGA melanoma dataset, the top 312 genes with a positive correlation (down to Spearman r = 0.5) with the prototypic EMT marker ZEB1, were also positively correlated with SNAI1, NFATc2, CDH2, and AXL, but negatively with MITF and CDH1." (PMID 30710146, 2019). "Interestingly, NFATC2 (nuclear factor of activated T-cells), a transcriptional regulator of TNF and TNF receptor expression in melanoma cell lines is also overexpressed in the chordoma samples and may be targeted by the downregulated miRNA miR-665." (PMID 36033338, 2022). "NFATc2+ melanomas expressed AXL, N-cadherin and ZEB1, but lacked MITF." (PMID 30710146, 2019).
sarcoma (30 papers, 2011 to 2025). A usually aggressive malignant neoplasm of the soft tissue or bone. "This positivity led to the consideration of a differential diagnosis of Ewing sarcoma, EWSR1::NFATC2- rearranged sarcoma, and mesenchymal chondrosarcoma for further assessment." (PMID 40323235, 2025). "In our review of the four cases reported in this study and previously published cases, almost all reported cases of EWSR1::NFATC2 sarcoma exhibited the FISH pattern with separation of red and green signals accompanied by 5' amplification of the EWSR1 locus." (PMID 38254207, 2024). "In terms of histology, EWSR1/FUS::NFATC2 sarcoma typically presents as an undifferentiated small round cell sarcoma." (PMID 38254207, 2024). "The latest research findings and novel treatment approaches for EWSR1/FUS::NFATC2 sarcoma involve molecular pathology research, immunotherapy, targeted therapy, and gene-editing techniques." (PMID 38254207, 2024). "In terms of clinical characteristics, EWSR1/FUS::NFATC2 sarcoma mainly occurs in young males, with a male-to-female ratio of approximately 3:1." (PMID 38254207, 2024). "In terms of clinical, radiological, histological, and FISH detection findings, EWSR1::NFATC2 fusion sarcoma exhibits distinct histopathological and molecular genetic features." (PMID 38254207, 2024). "These research results and novel treatment approaches provide new insights and directions for the treatment and management of EWSR1/FUS::NFATC2 sarcoma." (PMID 38254207, 2024). "In recent years, with the development of next-generation sequencing technology, some tumors associated with EWSR1 gene rearrangements have shown unique histological and molecular genetic characteristics, such as EWSR1/FUS::NFATC2 sarcoma." (PMID 38254207, 2024). "NKX2.2, which is a relatively specific marker for diagnosing Ewing sarcoma, can also be expressed in EWSR1/FUS::NFATC2 sarcoma." (PMID 38254207, 2024). "EWSR1::NFATC2 rearranged sarcomas are a group of rare round, undifferentiated sarcomas with clinicopathological features different from those of Ewing's sarcoma (ES) family and other non-ES sarcomas." (PMID 38254207, 2024). "In terms of prognosis, EWSR1/FUS::NFATC2 sarcoma typically requires treatment such as surgical resection, radiation therapy, and chemotherapy." (PMID 38254207, 2024). "Some studies have shown that the prognosis of EWSR1/FUS::NFATC2 sarcoma is related to factors such as age, tumor size, lymph node metastasis, and surgical resection." (PMID 38254207, 2024). "Immunohistochemical staining shows that EWSR1/FUS::NFATC2 sarcoma often expresses markers such as CD99, NKX3.1." (PMID 38254207, 2024). "Due to the focal expression of epithelial markers such as CK and EMA in some cases of EWSR1/FUS::NFATC2 sarcoma, combined with morphological features, it can be easily misdiagnosed as an myoepithelioma." (PMID 38254207, 2024). "This article reports four cases of EWSR1::NFATC2 sarcoma, reviews the literature, and explores the clinical and pathological characteristics as well as molecular genetic features of this tumor." (PMID 38254207, 2024). "Sarcomas with NFATC2 fusions tend to exhibit epithelioid features, while PATZ1 sarcomas are composed of largely undifferentiated round to ovoid neoplastic cells in a frequently sclerotic background." (PMID 36941503, 2023). "Significant differences in morphology, transcriptional profile, and behavior are found when comparing sarcomas harboring EWSR1::NFATC2 and FUS::NFATC2 fusions." (PMID 36555836, 2022). "CNV analysis showed simple karyotypes in all cystic lesions, while more complex karyotypes were found in NFATC2-rearranged sarcomas." (PMID 36555836, 2022). "Fusion analysis revealed two FUS::NFATC2 rearrangements in two cystic lesions and three EWSR1::NFATC2 rearrangements in one complex cystic lesion and two sarcomas." (PMID 36555836, 2022).
sarcoma (continued). "On the other hand, FUS::NFATC2-translocated sarcomas exhibited very complex genomic profiles, while in those cases harboring ESWR1::NFATC2 fusion, fewer genomic alterations were found." (PMID 36555836, 2022). "NFATc2-sarcomas include sarcomas with EWSR1–NFATc2, which commonly show an EWSR1 amplification pattern on fluorescence in situ hybridization, and FUS-NFATc2 fusions." (PMID 33919988, 2021). "NFATc2-rearranged sarcoma affects males and females with predominance of males at least in the first studies." (PMID 34203801, 2021). "Submitted] - reclassified as myoepthelioma-like sarcoma - had an EWSR1/NFATC2 fusion, adding to the growing morphological spectrum of this recently described gene fusion." (PMID 22588017, 2011). "FUS::NFATC2 sarcoma has a worse prognosis than EWSR1::NFATC2 sarcoma." (PMID 38254207, 2024). "NFATC2 sarcoma may show significant epithelioid features, while PATZ1 sarcoma usually has a sclerotic background." (PMID 38427070, 2024). "The fusion breakpoints and fusion types in EWSR1/FUS::NFATC2 sarcoma may impact the tumor's biological behavior and prognosis." (PMID 38254207, 2024). "In summary, the differential diagnosis of EWSR1/FUS::NFATC2 sarcoma is complex with many pitfalls." (PMID 38254207, 2024). "Immunohistochemically, CD99 is diffusely expressed in 50% of EWSR1/FUS::NFATC2 sarcoma cases." (PMID 36983010, 2023). "NFATC2 sarcomas express diffuse CD99 (like ES) in about 50% of cases; NKX2.2, dot-like keratin, and PAX7 positivity may also be observed." (PMID 36941503, 2023). "This category includes EWSR1/FUS::NFATC2 sarcomas and EWSR1::PATZ1 sarcomas." (PMID 36983010, 2023). "Higher expression levels of fusion transcripts found in EWSR1::NFATC2-rearranged sarcomas could also be an explanation for the malignant behavior." (PMID 36555836, 2022). "Additionally, recurrent fusion gene amplification is almost exclusively detected in the EWSR1::NFATC2-rearranged sarcomas." (PMID 36555836, 2022). "This phenomenon is described in several cases of EWSR1/FUS::NFATC2-rearranged sarcomas in which symptoms were present for years before diagnosis, suggesting that a pre-existing low-grade component may have undergone biological progression in a subset of patients." (PMID 36555836, 2022). "For certain situations, such as EWSR1::POU5F1 sarcoma and rare myoepithelial sarcoma, validation using EWSR1/FUS::NFATC2 fusion probe is necessary." (PMID 38254207, 2024). "For example, EWSR1/FUS::NFATC2 sarcomas feature a marked male predilection, and EWSR1::PATZ1 sarcomas can arise in a broad age range, in contrast to Ewing sarcoma." (PMID 38339014, 2024). "This suggests the possibility of EWSR1/FUS::NFATC2 sarcoma and can be validated using EWSR1::NFATC2 or FUS::NFATC2 fusion probe and NGS." (PMID 38254207, 2024). "Genetically and clinically different round cell sarcomas were recently identified: round cell sarcoma with EWSR1-non ETS (NFATC2 and PATZ1 being the most common ones), CIC-rearranged sarcomas and sarcomas with BCOR genetic alteration." (PMID 34514574, 2021). "Among the 30 cases with follow-up results, including the four cases reported in our study, the mortality rate of EWSR1/FUS::NFATC2 sarcoma is not high, even though it can exhibit local recurrence and lung metastasis." (PMID 38254207, 2024). "These mainly comprise EWSR1::NFATC2 and FUS::NFATC2 sarcomas and EWSR1::PATZ1 sarcomas." (PMID 36941503, 2023). "Case 10 tested negative for ES and Ewing-like tumours (CIC sarcoma and NFATC2-reaarranget tumour), but targeted NGS revealed a fusion between EWSR1 and ATF1." (PMID 36614077, 2022). "Given the suggested activation of mTOR in EWSR1-NFATc2 fusion positive sarcomas, and the conservation of the primary transactivation and regulatory domains of NFATc2 in EWSR1-NFATc2 fusion, we proceeded to assess the role of NFATc2 overexpression on mTOR in a tumor agnostic fashion." (PMID 34021224, 2021).
sarcoma (continued). "NFATC2 sarcoma may exhibit epithelioid features, and PATZ1 sarcomas often display a sclerotic background." (PMID 33114111, 2020). "Therefore, although EWSR1/FUS::NFATC2 sarcoma has a relatively specific FISH presentation, when diagnosing tumors with EWSR1/FUS::NFATC2 gene rearrangement, it is necessary to consider factors such as the clinical presentation, histological changes, treatment and prognosis." (PMID 38254207, 2024). "Additionally, the EWSR1/FUS::NFATC2 gene rearrangement feature can also be detected in simple bone cysts, but it does not harbour the amplification of the fusion gene and exhibits different clinical manifestations, histology, and prognosis compared to EWSR1/FUS::NFATC2 sarcoma." (PMID 38254207, 2024). "Round cell sarcoma with EWSR1-non-ETS fusions includes two distinct entities, the EWSR1::NFATc2- and the EWSR1::PATZ1-fusion sarcomas." (PMID 40948502, 2025). "The most common representative of these non-ETS GF entities is EWSR1::NFATC2 or FUS::NTAC2 sarcoma, followed by EWSR1::PATZ1 sarcoma." (PMID 38339014, 2024). "Among these, undifferentiated small round cell sarcomas (USRCSs) comprise multiple subcategories, including the recently described CIC-rearranged sarcomas, sarcomas with BCOR alterations, and non-ETS fused sarcomas (such as NFATC2 and PATZ1 sarcomas)." (PMID 38436779, 2024). "We report five patients with EWSR1/FUS::NFATC2-rearranged neoplasms, including one simple bone cyst (SBC), two complex cystic bone lesions lacking morphological characteristics of SBC, and two sarcomas." (PMID 36555836, 2022). "These tumors comprise a heterogeneous category of old and new or emerging entities including morphologically defined sarcomas/neoplasms with EWSR1::CREB fusions and unclassified sarcomas with non-ETS EWSR1 fusions such as EWSR1::PATZ1 and EWSR1::NFATC2 fusions." (PMID 39031200, 2024).
lung adenocarcinoma (14 papers, 2013 to 2024). A carcinoma that arises from the lung and is characterized by the presence of malignant glandular epithelial cells. "LEF1 is able to regulate glioblastoma stem-like cell self-renewal; NFATc2 enhances tumor-initiating phenotypes in lung adenocarcinoma." (PMID 29723215, 2018). "NFATc2 enhanced the CSC phenotype through the NFATc2/Sox2ALDH axis in lung adenocarcinoma." (PMID 36077186, 2022). "It was also reported that NFATC2 enhances tumor-initiating phenotypes in lung adenocarcinoma." (PMID 33013423, 2020). "Similarly, NFATc2 was overexpressed in lung adenocarcinoma tumor-initiating cells; it supported tumorigenesis in vivo and its knockdown in vitro reduced 60–70% tumor-spheres and restricted the renewability of tumor-spheres." (PMID 33014880, 2020).
pancreatic cancer (14 papers, 2014 to 2025). "Preliminary work has shown that NFATc2 interacts with other transcriptional partners, such as the oncogenic protein Sp1 in pancreatic cancer, and that carcinogenic effects are caused by the interaction of NFATc2 and Sp1." (PMID 36777697, 2022). "In more than 80% of pancreatic tumor tissue, such over-expression is caused by the amplification of NFATc2 on the chromosome 20q13." (PMID 30696421, 2019). "A more recent preliminary expression profile analysis carried out by our group showed the NFATc2- and Sp1-dependent regulation of integrin beta-3 in pancreatic cancer cells." (PMID 36777697, 2022). "The current study also showed the interaction between the transcription factor NFATc2 and the N-terminal domain of Sp1 in pancreatic cancer cells." (PMID 30696421, 2019). "The current study shows the interaction between the transcription factor NFATc2 and the N-terminal domain of Sp1 in pancreatic cancer cells." (PMID 30696421, 2019). "Recent investigations have shown the important role of the oncogenic transcription factor Sp1 in the transcriptional activity of NFATc2 in pancreatic cancer, in which interaction between binding partners occurs within the cell." (PMID 30696421, 2019). "Recent research has shown the importance of the transcription factor Sp1 in the transcriptional activity of NFATc2 in pancreatic cancer." (PMID 30696421, 2019). "In pancreatic cancer, the oncogenic transcription factor Sp1 (specificity protein 1) plays a central role in the transcriptional and functional activity of NFATc2." (PMID 30696421, 2019). "A possible new approach to treating pancreatic cancer is inhibiting the interaction between NFATc2 and Sp1." (PMID 30696421, 2019). "The present work is focused on NFATc2 because of its high expression intensity in pancreatic carcinoma." (PMID 28774282, 2017). "The oncogenic transcription partner Sp1 is important for the transcriptional and functional activity of NFATc2 in pancreatic carcinoma." (PMID 28774282, 2017). "The oncogenic transcription factor Sp1 plays an important role in the transcriptional and functional activity of NFATc2 in pancreatic carcinoma, in which the binding partners interact in the cell." (PMID 28774282, 2017). "Wnt5A and NFATc2 were also upregulated in expression in pancreatic cancer; inhibition of Wnt5A led to significant increases in drug induced apoptosis both in vitro and in vivo." (PMID 25401518, 2014). "One possible explanation may be the activating serine-threonine-rich and glutamine-rich domains of Sp1 that increase the transcription and function of NFATc2 in pancreatic cancer." (PMID 30696421, 2019). "In this respect, NFATc2 and Sp1 seem to play a key role in the progression of pancreatic cancer." (PMID 30696421, 2019). "NFATc2 and Sp1 seem to play a key role in the progression of pancreatic cancer." (PMID 30696421, 2019). "It remains unclear, however, to what extent Sp1 as a binding partner of NFATc2 has a direct influence on the transcriptional and functional activity of DNA in pancreatic carcinoma." (PMID 28774282, 2017). "Here, NFATc2 seems to have a key role in the progression of pancreatic carcinoma." (PMID 28774282, 2017). "When verifying the potential partner proteins Sp1 and MEF 2A (row 2 and 3) expressed in pancreatic carcinoma cells, Sp1 could also be precipitated as a binding partner of NFATc2." (PMID 28774282, 2017). "In pancreatic cancer, the proto-oncogene c-Fos, the tumor necrosis factor TNF-alpha, and the adhesion molecule integrin beta-3 are target genes of the interaction between Sp1 and NFATc2." (PMID 30696421, 2019). "For this purpose, pancreatic cancer cells were transiently transfected with ‘Silencer Negative Control’-siRNA or a silencer-RNA sequence for NFATc2 or Sp1, or both." (PMID 30696421, 2019).
pancreatic cancer (continued). "A prime example of this is the ‘nuclear factor of activated T-cells 2’ (NFAT2 = NFATc1), whose gene regulatory activity is primarily regulated on the level of subcellular localization and which we have previously shown to be a central governor of cell growth in pancreatic cancer." (PMID 25849100, 2015).